SFRP1 (secreted frizzled related protein 1)
Diseases named in the same sentence as SFRP1 in open-access papers (continued):
Sharing a sentence is not in itself a finding about the gene and the disease.
tumor (continued). "SFRP1 (Secreted frizzled-related protein 1) is a glycoprotein modulator of Wnt-signaling that has been observed to play both tumor suppressor and oncogenic roles in a number of human cancers and to also be subject to epigenetic regulation via DNA methylation or microRNA transcriptional silencing." (PMID 32370304, 2020). "Finally, it is essential to understand the exact role of SFRP1 in both physiological lobular involution and tumor development." (PMID 31947616, 2020). "SFRP1 might act as a tumor suppressor to reverse taxane resistance of LAD cells by inactivating Wnt signaling, as indicated by both in vitro and in vivo experiments." (PMID 33224874, 2020). "In addition, evidence suggests that SFRP1 transcription is frequently regulated by epigenetic events, such as DNA methylation alterations and chromatin histone modifications, in various tumor models." (PMID 33224874, 2020). "Downregulation of sFRP1 and Smad4 could activate Wnt/β-catenin signaling pathway, thereby promoting tumor cell invasion and metastasis." (PMID 33310972, 2020). "Another potential tumor suppressor upregulated in topotecan-resistant patients is SFRP1, a member of the secreted frizzled-related protein (SFRP) gene family that shares sequence homology with Fzd receptors, can sequester Wnt ligands and antagonize Wnt signaling." (PMID 31195594, 2019). "Importantly, addition of SFRP1 recombinant protein in Rab37 knockdown cells suppressed sphere formation in vitro and tumor initiation ability in vivo." (PMID 30158579, 2018). "Furthermore, many authors have demonstrated that SFRP1 suppresses tumor growth and inhibits Wnt signaling." (PMID 30394013, 2018). "Similarly, secreted frizzled-related protein-1 (SFRP1) is a well-known inhibitor of Wnt/β-catenin signaling and patients with lower SFRP1 expression level in tumor tissue have poor overall survival rate in HCC." (PMID 29977206, 2018). "Moreover, in Hu’s study, it was shown that Wnt antagonists WIF1-Fc and SFRP1-Fc inhibit Wnt signalling and exert antitumour activity by inducing apoptosis in tumour cells, which indicates that Wnt antagonists would be a promising molecular treatment for HCC." (PMID 28899352, 2017). "SFRP1 can block Wnt signaling pathway to suppress tumor proliferation and metastasis." (PMID 27385214, 2016). "Furthermore, we found that the repression efficacy of silencing miR-1207 on tumor sphere formation was dramatically abolished by downregulation of SFRP1, AXIN2 and ICAT." (PMID 26337084, 2015). "Concerning SFRP1 our data are consistent with published studies, which provide evidence for hypermethylation and consequential underexpression of SFRP1, promoting tumor formation." (PMID 26291085, 2015). "We identified three tumour suppressor genes associated with Wnt signalling, namely, AXIN2, DKK3 and SFRP1, that could potentially be suppressed by miR-582-3p." (PMID 26468775, 2015). "Tumor samples lacking SFRP1 protein expression also exhibited loss of BDNF protein expression and vice versa." (PMID 25036590, 2014). "The mechanisms by which tumor suppressor SFRP1 influences carcinogenic properties of cancer cells do not rely on Wnt signaling, thereby demonstrating the complexity of tumor associated signaling pathways." (PMID 25033833, 2014). "SFRP1 protein is a soluble Wnt antagonist, which has been suggested as tumor suppressor." (PMID 24738045, 2014). "Still SFRP1 may confer growth-inhibitory signals in such tumor lines via independent or rather different pathways which we would like to decipher in more detail." (PMID 25036590, 2014). "We detected different levels of SFRP1 expression mostly located in the tumor tissue." (PMID 25033833, 2014). "In contrast to the DNA repair gene O6-methylguanine-DNA methyltransferase (MGMT), which has been found to be methylated in the macroscopic field of some CRCs, in our study epithelial SFRP1 hypermethylation was only present in areas closely localized to the tumor (NAT)." (PMID 25405986, 2014).
tumor (continued). "To determine whether the expression of SFRP1 and β-catenin correlate with clinicopathological tumor parameters among the 78 BTC samples, we performed chi-square tests." (PMID 24594839, 2014). "Our results suggest that the myofibroblast-derived SFRP1 protein might be a paracrine inhibitor of epithelial proliferation in NAT areas and loss of this signal may support tumor proliferation in CRC." (PMID 25405986, 2014). "Furthermore the SFRP1 gene displays a high methylation frequency in cholangiocarcinoma, suggesting the possibility of its tumor-specific inactivation." (PMID 24594839, 2014). "The putative tumor suppressor SFRP1 is an important inhibitor of this signaling pathway." (PMID 25036590, 2014). "SFRP1 is a tumor suppressor, which has already been associated not only to carcinogenesis but also, to some extent, with the metastatic potential of cancer cells." (PMID 24194935, 2013). "By far the biggest difference in methylation between tumour and normal could be seen for SFRP1, which was hypermethylated in all tumour samples." (PMID 22672427, 2012). "Thus sFRP-1 acts as a tumor suppressor and its restoration attenuated the clear cell renal cancer tumor phenotype." (PMID 22325146, 2012). "Patched Homolog 1 (PTCH1) is the SHH receptor and is the most commonly mutated tumor suppressor in BCC, whereas adenomatous polyposis coli (APC), secreted frizzled-related protein 1 (SFRP1), SFRP2, SFRP4, and SFRP5 are all negative regulators of the canonical WNT pathway." (PMID 23284750, 2012). "sFRP1 has also been shown to block motility and invasion of other types of tumor cells." (PMID 19473496, 2009). "Furthermore, we show that stable expression of sFRP1 in MDA-MD-231 cells has a dramatic effect on the ability of the cells to grow as tumor xenografts in nude mice." (PMID 19473496, 2009). "Our results show a dramatic 130-fold decrease in the expression of SFRP-1 in the tumour." (PMID 18212756, 2008). "SFRP1 is downregulated and versican is upregulated in both tumor types." (PMID 17389037, 2007). "These transient and long-term effects of SFRP1 on different HCC cells support the notion that SFRP1 as a candidate tumor suppressor genes could be involved in hepatocarcinogenesis." (PMID 17626620, 2007). "We and others have reported that TMS1, 14-3-3sigma and WT1 genes are methylated more frequently in clear cell tumours than in other tumour types, whereas methylation of SFRP1, 18S and 28S ribosomal DNA genes is more frequently detected in nonclear cell tumours, such as the serous type." (PMID 16479257, 2006). "Therefore, the increase in SFRP1 expression we observed at the end of the sixth month, may contribute to the development and progression of the tumor along with other tumor genes." (PMID 40365190, 2025). "Although Sfrp1 is a Wnt pathway-related factor, its impact on tumor tissues remains unknown." (PMID 38625488, 2024). "Further functional experiments demonstrated that the overexpression of SFPR1 in KYSE-70 and KYSE-140 cell lines could significantly increase cell proliferation in vitro or xenograft tumour growth in vivo, while SFRP1 knockdown in KYSE-450 and KYSE-520 cells exhibited the opposite effects." (PMID 39419971, 2024). "In addition, the tumor weight was significantly lower in Sfrp1 KO mice than in WT mice (p < 0.05)." (PMID 38625488, 2024). "Furthermore, Sfrp1 may promote tumor growth by contributing to the maintenance of CSCs via Wnt signaling." (PMID 38625488, 2024). "Therefore, we examined the effect of Sfrp1, which is expressed in some tumor ECs, on CSCs." (PMID 38625488, 2024). "In contrast, CMTs with Metpos status were mostly negative for SFRP1 with occasional weak or focal positivity (M3 + 4), and with strongest positivity found associated with histologically normal tissue around the tumour margins." (PMID 37402051, 2023). "Our results support the hypothesis that a lack of SFRP1 could have a causal role in early breast carcinogenesis." (PMID 37190179, 2023).
tumor (continued). "However, tumor promoting roles for SFRP1 and SFRP2 have been reported in cancer." (PMID 37091166, 2023). "In this work, the positive correlation between SFRP1 and immune cells suggested that it could be one of the related genes that affected the tumor microenvironment of OSCC, especially in terms of the abundances of mast cells, T-helper cells, eosinophils cells, T cells and Th1 cells." (PMID 35892344, 2022). "Our findings suggest that SFRP1 may act as an oncogene in topotecan-treated patients, or alternatively, tumor cells overexpressing SFRP1 may be innately more resistant to the elimination of rapidly proliferating tumor cells." (PMID 31195594, 2019). "Therefore, we proposed that cancer stemness and tumor initiation properties could be inhibited by treatment with SFRP1 recombinant protein." (PMID 30158579, 2018). "In addition, HBP1 and SFRP1 included in the models are known to function as suppressors of cancer progression by suppressing β-catenin transactivation, and cell adhesion-related genes are involved in tumor invasion or metastasis." (PMID 29270240, 2017). "However, these researchers did not evaluate the role TGF-β plays in their model of tumorigenesis and therefore future research will be directed identifying how loss of SFRP1 together with TGF-β1, EGR2 upregulation, and additional tumor initiating pathways promote mammary carcinogenesis." (PMID 28687085, 2017). "However, the availability of SFRP1 expression as a prognostic marker is highly limited in early stage of cancer, as SFRP1 expression does not reflect the tumor grade or lymph node metastasis status associated with poor prognosis." (PMID 28178355, 2017). "Our results suggest that SFRP1 may serve as a candidate tumor suppressor gene for BTC." (PMID 24594839, 2014). "We presume that the paracrine, anti-proliferative effect of myofibroblast-derived SFRP1 may inhibit field cancerization in NAT and TA areas, and so cancer-associated myofibroblasts may support the uncontrolled tumor cell proliferation by an epigenetically silenced Wnt inhibitory signal." (PMID 25405986, 2014). "Since sFRP1 is a secreted protein, it could act extrinsically on cells in the tumor environment." (PMID 19473496, 2009). "On the other hand, our data also implied that SFRP1 as a tumor suppressor gene and secreted protein for inhibiting Wnt-β-catenin could be employed for cancer therapy through transfecting the gene into tumor, and injecting the active protein as surroundings niche." (PMID 17626620, 2007). "Thus, our study clearly demonstrates that sFRP1 fulfills its proposed tumor suppressor function." (PMID 17897439, 2007). "SFRP1 belongs to the SFRP protein family, which exhibits a dual function: it inhibits the Wnt pathway (acting as a tumor suppressor) and promotes tumor progression under specific conditions." (PMID 41209699, 2025). "SFRP1 interacts with the FGFR2 receptor, activating downstream HIF1 signaling pathways to enhance tumor stemness and EMT activity, thereby accelerating tumor metastasis." (PMID 40225580, 2025). "SFRP1 overexpression renders GBM quiescent and increases the overall survival of tumor-bearing mice." (PMID 40770193, 2025). "Among the Wnt-related genes relevant to PCa, Wnt3a, Wnt5a, Fzd7, sFRP1, and ROR2 stand out due to their roles in modulating tumour behaviour under hypoxic conditions." (PMID 41007281, 2025). "Next, we examined the effects of Sohlh1 on SFRP1 expression in GSLCs and GSLC‐derived tumour tissues." (PMID 40418209, 2025). "Mechanistically, SFRP1 from CFD+ iCAFs binds FGFR2, activating the HIF1 signaling pathway to enhance tumor stemness, EMT, and CRLM progression." (PMID 40225580, 2025). "these genes, Insulin Like Growth Factor 1 (IGF1) and Secreted Frizzled Related Protein 1 (SFRP1), were found to be down-regulated in tumor tissues, while the third gene, SDC1, also known as Syndecan 1, was found to be up-regulated in tumor tissues." (PMID 41209699, 2025).
tumor (continued). "SFRP1-producing CAFs interacts with tumor cells via SFRP1-FGFR2-HIF1 axis, facilitating tumor stemness and EMT." (PMID 40225580, 2025). "The dysregulated Wnt antagonists SFRP1 and NOTUM were found at the Q–A transition, and independent overexpression of either induced a pronounced astrocytic shift in tumor cell morphology, transcriptome, and methylome." (PMID 40770193, 2025). "SERPINB5, SFRP1, and TFRC exhibited higher expression levels in PAAD tumor samples, consistent with the gene expression data from the HPA database." (PMID 41595468, 2025). "A heatmap based on log2-fold change values demonstrated general overexpression of Wnt pathway genes in cancers, except for genes such as CAMK2A, SFRP1, and SOX17, which were underexpressed in several tumor types." (PMID 40002717, 2025). "Compared with normal tissues, the top three downregulated genes in the tumor tissues were FABP4, SAA1, and SFRP1, while the top three upregulated genes were COMP, COL10A1, and MMP11." (PMID 40936892, 2025). "SERPINB5, SFRP1, and TFRC showed elevated expression levels in PAAD tumor samples compared to normal samples." (PMID 41595468, 2025). "However, the cells that produce Sfrp1 in the tumor environment and its function remain unclear." (PMID 38625488, 2024). "To test the effect of Sfrp1 on tumor tissues, we determined the percentage of CD44+ CD133+ tumor cells in Sfrp1 KO and WT mice." (PMID 38625488, 2024). "Within the yielded 8 subclusters in the SHH tumor dataset, clusters 2, 5, and 7 contained cells that expressed early SHH MB markers, such as SFRP1 and HHIP5,26." (PMID 39659836, 2024). "In the lung, however, metastatic cells are reactivated by aged fibroblasts through secreted sFRP1, which is an antagonist of Wnt5a, resulting in decreased AXL signaling, enhanced MER activation and tumor cell proliferation." (PMID 37296983, 2023). "The study's findings reveal that SFRP1 Inhibited xenograft tumour growth in two CCA cell lines, reflected by smaller tumour mass and lower tumour weight." (PMID 38050190, 2023). "We also detected the levels of the main proteins involved in tumor progression, DKK1 and SFRP1, by ELISA and cell senescence by β-galactosidase tests." (PMID 37374009, 2023). "In a recent study, integrated MSP and immunohistochemical analysis showed SFRP1 promoter hypermethylation and subsequent downregulation in EOC tumor samples." (PMID 37123549, 2023). "Increased concentrations of SFRP1 and SFRP5 were present in stage III NSCLC samples, while the tumour samples with high pleural invasion (PL2) had an increased level of SFRP2." (PMID 37999144, 2023). "Interestingly, the bioinformatics analysis of mRNA SFRP1 expression found significantly decreased SFRP1 gene in tumour tissues compared to normal counterparts, in various cancers, suggesting that SFRP1 protein could possibly have different functions in different types of cancer." (PMID 37999144, 2023). "In order to assess the potential of SFRP1 to act as a tumor suppressor in pre-invasive lesions, we also examined the phenotype of the MCF10DCIS cell line following the increase in SFRP1 expression." (PMID 37190179, 2023). "As secreted glycoproteins, SFRP1 and SFRP2 are thought to be primarily tumor suppressive as they bind and sequester WNT ligands to modulate cancer cell growth, cell polarity, transformation and cancer stem cell activity." (PMID 37091166, 2023). "For the AC subtype, significantly higher concentrations of SFRP1 and SFRP5 in tumour samples compared to NT were detected (p = 0.022 and p = 0.011, respectively), while the level of SFRP2 protein was reduced in tumour samples (p < 0.001)." (PMID 37999144, 2023). "Taken together, we indicated that miR-26a-5p played as a tumor suppressor, and DNMT3A acted as an oncogene to repress SFRP1 expression by enhancing DNA methylation." (PMID 35860691, 2022).
tumor (continued). "Treatment with IL30 also upregulated tumor progression genes, such as Ar (3.27 times), Bcl2 (3.25 times), IL6 (3.90 times), Cav2 (7.60 times), Ndrg3 (4.5 times), Sept7 (4.10 times) and Sfrp1 (7.46 times)." (PMID 36224639, 2022). "Consistent with the observed increase in WNT related genes in tumor cells, we saw high scores for WNT-related interactions (ligands Sfrp1 and Wnt5a and receptors Fzd6, Fzd7 and Lrp6) and significant BMP-related interactions (e.g. from Bmp4 with Bmpr1a)." (PMID 35600339, 2022). "SFRP1 and SFRP2 are expressed in stromal myofibroblasts and are downregulated from typical adjacent tumor (normal tissue adjacent to the tumor, NAT) tissues toward the tumor." (PMID 35712512, 2022). "The sFRP family contains five glycoproteins, SFRP1, SFRP2, SFRP3 (FRZB), SFRP4, and SFRP5, which are generally regarded as tumor suppressors owing to their ability to negatively regulate the Wnt pathway." (PMID 35204808, 2022). "In addition, 5-aza-2′deoxycytidine (5-aza-dC) is reported to restore sFRP1 expression in laryngeal cancer cell lines, which led to decreased cell proliferation and colony-forming and sensitized cells to cisplatin in vitro, and tumor growth was impaired in xenografts in vivo." (PMID 35204808, 2022). "The methylation level in the methylated EOC tumor samples ranged from 4 to 97% for HOXA9; 7–89% for HIC1; 4–97% for SOX1; 4–95% for DAPK1; 5–97% for SFRP1; 6–99% for SPARC and 4–98% for RASSF1A gene, respectively." (PMID 34778370, 2021). "It is not clear why SFRP1 protein have the opposite effects between LNCaP and VCaP cells but this could explain in some manner the diverse responses that exist in different cell types associated with tumor heterogeneity." (PMID 32694934, 2020). "In this study, we presented the evidence that in the tumor microenvironment affected by NE, stromal HSCs within the tumor microenvironment of HCC acquire the capacity to secrete sFRP-1 and thereby promote phenotypic progression in HCC cells." (PMID 32293507, 2020). "Specifically, CDH4, SFRP1, and ERF which are indicated to be tumor suppressor genes by the TSGene 2.0 database and have support from the literature as well; however, our method identified them as monotonically increasing genes." (PMID 33273919, 2020). "A study in 2011 found that SFRP-1 and the SFRP-like molecule V3Nter can inhibit β-catenin-activated tumor cells growth in vivo, though another study argues that sFRPs have dual effects on Wnt/β-catenin signaling depending on various factors." (PMID 33262947, 2020). "Indeed, the lack of SFRP1 is associated with both tumor development and patient prognosis." (PMID 31947616, 2020). "We demonstrated that SFRP1 protein increased ERG expression by promoting cellular migration in vitro and increasing tumor growth in vivo in PCa cells with the TMPRSS2-ERG fusion." (PMID 32694934, 2020). "The SFRP1, SFRP2, and WIF1 methylation levels in tumor tissues were significantly higher than that in adjacent non-tumor tissues (P < 0.001)." (PMID 31830937, 2019). "In this study, we found that the promoter methylation level of SFRP1, SFRP2, and WIF1 was enormously higher in tumor tissues than that in adjacent non-tumor tissues." (PMID 31830937, 2019). "For further survival analysis, the cut-off values of SFRP1, SFRP2, and WIF1 methylation for distinguishing the survival status accounted for 10.0, 50.0, and 50.0% in tumor tissues." (PMID 31830937, 2019). "The SFRP1, SFRP2, and WIF1 methylation levels in tumor tissues were significantly higher than that in adjacent non-tumor tissues (Mann-Whitney U test, P < 0.001)." (PMID 31830937, 2019). "Reconstitution experiments indicate that SFRP1 secretion is crucial for Rab37-mediated cancer stemness suppression and treatment with SRPP1 recombinant protein reduces xenograft tumor initiation ability." (PMID 30158579, 2018).